LTK (leukocyte receptor tyrosine kinase)
Description:
Receptor with a tyrosine-protein kinase activity. Following activation by ALKAL1 or ALKAL2 ligands at the cell surface, transduces an extracellular signal into an intracellular response. Ligand-binding to the extracellular domain induces tyrosine kinase activation, leading to activation of the mitogen-activated protein kinase (MAPK) pathway. Phosphorylates almost exclusively at the first tyrosine of the Y-x-x-x-Y-Y motif (By similarity). The exact function of this protein is not known; studies with chimeric proteins demonstrate its ability to promote growth and specifically neurite outgrowth, and cell survival. Involved in regulation of the secretory pathway involving endoplasmic reticulum (ER) export sites (ERESs) and ER to Golgi transport.
Synonyms: TYK1
Tractability: Small molecule: a high-quality ligand is known; it belongs to a druggable protein family. Antibody: UniProt places it where antibodies can reach, with high confidence; its Gene Ontology location is reachable by antibodies, with high confidence; UniProt predicts a signal peptide or a membrane-spanning region. PROTAC: a small molecule that binds it is known.
Target class: Tyrosine protein kinase Alk family; Enzyme; TK protein kinase group; Protein Kinase; Kinase
Safety:
Unwanted effects reported when the protein is acted on. In parentheses: how it was acted on, where the effect was seen, and who reports it.
heart disease (cardiovascular system; source: Force et al. (2011))
Gene: Protein-coding gene on chromosome 15 (41,503,634 to 41,513,887, reverse strand). Ensembl gene ENSG00000062524.
Subcellular location: Cell membrane
Subcellular location (Human Protein Atlas): Vesicles
Pathways (Reactome):
Signal Transduction: Signaling by LTK
Gene Ontology:
Molecular function: protein binding; protein kinase activity; protein tyrosine kinase activity; receptor signaling protein tyrosine kinase activator activity; transmembrane receptor protein tyrosine kinase activity; ATP binding
Biological process: cell population proliferation; cell surface receptor protein tyrosine kinase signaling pathway; cellular response to retinoic acid; negative regulation of apoptotic process; peptidyl-tyrosine autophosphorylation; positive regulation of cardiac muscle cell apoptotic process; positive regulation of neuron projection development; positive regulation of phosphatidylinositol 3-kinase/protein kinase B signal transduction; protein phosphorylation; regulation of cell population proliferation; regulation of neuron differentiation; signal transduction
Cellular component: membrane; plasma membrane; receptor complex
Genetic constraint (gnomAD): Loss-of-function variants: 115 observed, 94.54 expected, observed/expected ratio (o/e) 1.22, 90% interval 1.04 to 1.42. The synonymous counts are far from expectation, so gnomAD's model fits this gene poorly and the ratio says little. Missense variants: 1,235 observed, 1,084.8 expected, observed/expected ratio (o/e) 1.14, 90% interval 1.09 to 1.19. Synonymous variants: 558 observed, 455.44 expected, observed/expected ratio (o/e) 1.23, 90% interval 1.14 to 1.31.
Homologues: Orthologues: chimpanzee LTK (99% identical), macaque LTK (96% identical), rabbit LTK (88% identical), mouse Ltk (79% identical), rat Ltk (77% identical). Paralogues in human: ALK (54% identical), INSR (21% identical), ROS1 (21% identical), IGF1R (21% identical), INSRR (20% identical), FLT4 (20% identical), CSF1R (19% identical), TIE1 (19% identical), PDGFRB (19% identical), AXL (18% identical), FLT1 (18% identical), PDGFRA (18% identical), and 41 more.
Diseases named in the same sentence as LTK in open-access papers:
LTK is named in the same sentence as 34 diseases in open-access papers, as found by Europe PMC text mining. Sharing a sentence is not in itself a finding about the gene and the disease. The quoted sentences say what the papers report.
lupus (6 papers, 2012 to 2025). "Previous studies have found that LTK is expressed in B lymphocyte precursor cells, and its gain-of-function is associated with the pathogenesis of systemic lupus erythematosus pathogenesis through upregulating self-reactive B cells." (PMID 39851522, 2025). "Interestingly, a gain-of-function mutation in LTK was identified in the LTK kinase domain in lupus-prone mice and in patients with systemic lupus erythematosus." (PMID 40634511, 2025). "Notably, LTK’s gain-of-function polymorphism in human is associated with systemic lupus erythematosus (SLE), a chronic autoimmune disease characterized by autoantibodies production and multi-organ inflammation." (PMID 32059449, 2020).
lung carcinoma (5 papers, 2012 to 2024). "Accordingly, we investigate the evolutionary histories of anaplastic lymphoma kinase (ALK)—which can underlie tumorigenesis in neuroblastoma, nonsmall cell lung cancer, and anaplastic large-cell lymphoma—its close relative leukocyte tyrosine kinase (LTK) and their candidate ligands." (PMID 33196781, 2021). "In our present study, LTK knockdown was used as a positive control, providing a reliable reference for assessing its role in lung cancer progression and for comparative evaluation of PIK3C2G’s functional impact in A549 cells." (PMID 39950101, 2024). "Also, constitutively activated ALK is known to carry prognostic value in cancers such as lung cancer and ALCL, thus providing further evidence that mutations in LTK that induce constitutive signaling may provide clinically important information." (PMID 22347506, 2012).
non-small cell lung carcinoma (5 papers, 2012 to 2024). A group of at least three distinct histological types of lung cancer, including non-small cell squamous cell carcinoma, adenocarcinoma, and large cell carcinoma. "Subsequent studies by the same research group revealed that high expression of LTK in non-small cell lung cancer (NSCLC) patients correlated with a 3-fold risk of metastasis in stage I/II disease." (PMID 22347506, 2012). "LTK gene is not reported with any functional oncogenicity till now, but recently CLIP1-LTK fusion has been reported in non-small cell lung cancer." (PMID 37287033, 2023).
acute myeloid leukemia (2 papers, 2012 to 2021). Acute myeloid leukemia (AML) is a group of neoplasms arising from precursor cells committed to the myeloid cell-line differentiation. "Further implicating LTK dysregulation in leukemia, the LTK gene was found to be overexpressed among 85 acute myeloid leukemia (AML) samples." (PMID 22347506, 2012).
leukaemia (2 papers, 2012 to 2023). "Deletion of LTK is associated with reduction of ER sites and slow ER to Golgi body transport and thus regulate proteostasis, it is found to be overexpressed in human leukaemia." (PMID 37287033, 2023). "Leukocyte tyrosine kinase (LTK) is a receptor tyrosine kinase reported to be overexpressed in human leukemia." (PMID 22347506, 2012).
myeloma (2 papers, 2023 to 2025). "LTK mutations may cause myeloma and can be used as biomarkers to detect specific targets of myeloma." (PMID 36816364, 2023). "Further analysis of LTK expression by qPCR was conducted in smouldering myeloma (SMM), newly diagnosed MM, relapsed/refractory MM, human myeloma cell lines (HMCLs), and healthy donor plasmablasts expanded from CD19+ peripheral blood cells." (PMID 40634511, 2025). "Further analysis revealed the primary isotype of LTK in MM cells as the LTK-202 isoform, which lacks exon 7 and localizes to the ER, as confirmed by co-localization studies in HeLa cells and primary myeloma samples." (PMID 40634511, 2025). "Our findings that LTK is expressed in MM cells, combined with the observation that this kinase was activated by secretory flux, make LTK a promising drug target for myeloma therapy." (PMID 40634511, 2025). "Subsequent qPCR analysis confirmed LTK expression across various stages of MM, including smouldering myeloma, newly diagnosed MM, and relapsed/refractory MM." (PMID 40634511, 2025). "Our work establishes LTK as a promising novel target for myeloma therapy." (PMID 40634511, 2025). "We also confirmed LTK localization in an HMCL, RPMI-8226, and in a primary myeloma patient sample, finding it localized to intracellular ER-like membranes." (PMID 40634511, 2025). "LTK is a paralog of anaplastic lymphoma kinase ALK, and is only expressed in myeloma cells following the rare event of an ALK-translocation; hence, ALK-inhibitors have not generally been used in myeloma therapies." (PMID 40634511, 2025). "Taken together we confirm that myeloma cells express LTK, but not ALK, and that the main isoform of LTK in myeloma cells localizes to the ER and can be inhibited by ALK inhibitors." (PMID 40634511, 2025). "We found that the majority of patients (83%) had myeloma cells expressing LTK, but not ALK (0.1%)." (PMID 40634511, 2025).
Anxiety (1 paper, 2023). Intense feelings of nervousness, tension, or panic often arise in response to interpersonal stresses. "The expression of ALK, together with LTK, in the hippocampus and amygdala is associated with memory and anxiety." (PMID 37892172, 2023). "Interestingly, ALK KO mice show enhanced cognitive performance and reduced anxiety, while LTK KO mice do not show any significant changes." (PMID 37892172, 2023).
autoimmune disease (1 paper, 2008). A disorder resulting from loss of function or tissue destruction of an organ or multiple organs, arising from humoral or cellular immune responses of the individual to their own tissue constituents. "Finally, our data suggest simple, visual in vivo screens for LTK inhibitors which may be of utility considering the growing links of these RTKs to autoimmune disease." (PMID 18369445, 2008).
hepatocellular carcinoma (1 paper, 2023). A malignant tumor that arises from hepatocytes. "LTK is a common up-regulated target gene in stages I-IV of hepatocellular carcinoma, which is mainly involved in tumor immunity and signal transduction." (PMID 36816364, 2023).
idiopathic pulmonary fibrosis (1 paper, 2024). Idiopathic pulmonary fibrosis (IPF) is a nonneoplastic pulmonary disease that is characterized by the formation of scar tissue within the lungs in the absence of any known cause. "We identified one transcript, killer cell lectin like receptor 1 (KLRF1), as differentially expressed between idiopathic pulmonary fibrosis (IPF) and systemic sclerosis-associated ILD (SSc-ILD), and identified two transcripts (VCAN, LTK) associated with IPF expression against other ILD subtypes." (PMID 39625896, 2024).
lung adenocarcinoma (1 paper, 2024). A carcinoma that arises from the lung and is characterized by the presence of malignant glandular epithelial cells. "Indicating that both PIK3C2G and LTK contribute to the metastatic potential of lung adenocarcinoma cells." (PMID 39950101, 2024). "These distinct effects suggest that PIK3C2G and LTK regulate different aspects of cell cycle progression, highlighting their unique roles in lung adenocarcinoma biology." (PMID 39950101, 2024). "Cells transfected with siRNAs targeting either PIK3C2G or LTK exhibited markedly reduced growth rates compared to the control group, suggesting that both genes could play important roles in supporting cell proliferation in lung adenocarcinoma." (PMID 39950101, 2024).
lupus erythematosus (1 paper, 2025). An autoimmune, connective tissue chronic inflammatory disorder affecting the skin, joints, kidneys, lungs, heart, and the peripheral blood cells. "LTK variants also have evidence of being involved in lupus erythematosus, an autoimmune disease." (PMID 40883583, 2025).
myeloid sarcoma (1 paper, 2023). A tumor mass composed of myeloblasts or immature myeloid cells.
T-cell lymphoma (1 paper, 2023). "Moreover, missense mutations were detected in CD44 and CD19 (associated with acute myeloid leukemogenesis), LTK (associated with poorly differentiated adenocarcinoma), NOTCH2 (associated with diffuse large B-cell tumorigenesis), and CNTN2 (associated with T-cell lymphoma)." (PMID 36871023, 2023).
Type 2 diabetes (1 paper, 2025). "Annotation of LTK via STRING40 for protein-protein interactions has elucidated two potential pathways through which LTK may be participating in Type 2 diabetes." (PMID 40883583, 2025).
cancer (12 papers, 2012 to 2025). A tumor composed of atypical neoplastic, often pleomorphic cells that invade other tissues. "Having a potential therapeutic agent available makes the identification of potential activating LTK mutations in cancer all the more intriguing." (PMID 22347506, 2012). "The LTK pathway has been implicated in autoimmunity, neuronal development, and cancer." (PMID 33391411, 2021). "The similarity in the location of these ALK mutations, and thus the corresponding LTK mutations investigated in our study, to other activating tyrosine kinase domain mutations in cancer underscores the important consequences of mutation of this region of tyrosine kinases." (PMID 22347506, 2012). "Such insights will enable translational research toward interventions that successfully target the cellular function of ALK and LTK in human cancers." (PMID 33196781, 2021). "Both ALK and LTK play key roles in human cancers, whereas the ALK homolog in D. melanogaster directs gut and nervous system development and is associated with ethanol sensitivity and learning." (PMID 24379806, 2013). "While further research is needed to elucidate the role of LTK in human cancer, the potential for improved prognosis is significant if LTK-driven neoplasms can be identified and met with targeted treatments." (PMID 22347506, 2012). "Our work suggests that the similarities between ALK and LTK may be exploited for treatment options if LTK is found to have a role in driving certain cohorts of cancer patients." (PMID 22347506, 2012). "This suggests that LTK dysregulation may also have important consequences for cancer progression in this tumor type." (PMID 22347506, 2012). "Though much regarding the function of LTK remains unknown, it shares a high degree of similarity with anaplastic lymphoma kinase (ALK), which is found mutated in human cancer." (PMID 22347506, 2012). "While the size of the patient population with cancers containing activating LTK mutations, if any, is not yet known, advances in genomic sequencing, which will provide data for the personalization of therapeutic treatments for patients, makes the identification of such a population significant." (PMID 22347506, 2012). "Activation of Anaplastic lymphoma kinase (ALK) and leukocyte tyrosine kinase (LTK) by their cognate cytokines ALKAL2 and ALKAL1 plays important roles in development, metabolism, and cancer." (PMID 40208865, 2025). "It remains to be determined whether or not activating LTK mutations are present in human cancer." (PMID 22347506, 2012). "In addition to its role in cancer, ALK and its receptor family member Leukocyte tyrosine kinase receptor (LTK) have a key role in the normal physiology of the central nervous system." (PMID 39138146, 2024). "Disease outcomes relative to gene expression of ALK, LTK, PTN, and MK in clinical cancer specimen." (PMID 23267434, 2012). "An analysis of 18 published gene expression data sets from different cancers shows that overexpression of ALK, its smaller homolog LTK (leukocyte tyrosine kinase) and the ligands PTN and MK in cancer tissues from patients correlate significantly with worse course and outcome of the disease." (PMID 23267434, 2012).
tumor (4 papers, 2012 to 2024). "Abnormal activation and mutation of LTK regulate the growth and apoptosis of tumor cells and affect the occurrence and progression of many types of tumors." (PMID 36816364, 2023). "In addition, LTK also signals through the PI3K-AKT-mTOR pathway in order to maintain survival signals in tumor cells." (PMID 27974047, 2016). "Signaling and transforming activity of mutated LTK proteins are evident in cells of hematopoietic and epithelial origin, as well as in cells used to model neuronal differentiation, suggesting aberrant activation of LTK may play a role in neoplastic disease of multiple cell types." (PMID 22347506, 2012).
LTK also shares sentences with these, for which no sentence is quoted: neuroblastoma (2 papers); adrenal gland benign tumor (1); asthma (1); benign tumor (1); cardiac arrhythmia (1); dermatitis (1); endometriosis (1); gastric cancer (1); Graves disease (1); ischemic cardiomyopathy (1); multiple myeloma (1); non-Hodgkin lymphoma (1); pheochromocytoma (1); prostate carcinoma (1); pulmonary hypertension (1); rectal NETs (1); systemic sclerosis (1).